MIR93 (microRNA 93)
Synonyms: hsa-mir-93; MIRN9; MIRN93; miR-93
Gene: MicroRNA gene on chromosome 7 (100,093,768 to 100,093,847, reverse strand). Ensembl gene ENSG00000207757.
Gene Ontology:
Biological process: miRNA-mediated post-transcriptional gene silencing
Cellular component: RISC complex
Diseases named in the same sentence as MIR93 in open-access papers:
MIR93 is named in the same sentence as 10 diseases in open-access papers, as found by Europe PMC text mining. Sharing a sentence is not in itself a finding about the gene and the disease. The quoted sentences say what the papers report.
ovarian carcinoma (1 paper, 2015). A malignant neoplasm originating from the surface ovarian epithelium. "Our results show that MIR93 mRNA expression was significantly lower in ovarian carcinomas, borderline tumors, and metastatic omentum, and was negatively associated with differentiation and FIGO staging in ovarian carcinoma." (PMID 25649143, 2015). "MIR-93 mRNA expression in normal ovarian tissue, benign tumors, borderline tumors, primary ovarian carcinomas, and metastatic omentum was quantified." (PMID 25649143, 2015). "MIR-93 mRNA expression was significantly lower in ovarian carcinomas and borderline tumors than in normal ovarian tissues (p < 0.05), and was lower in metastatic omentum than in relative primary ovarian carcinomas (p < 0.05)." (PMID 25649143, 2015).
tumor (4 papers, 2017 to 2024). "MIR-93 promotes tumor angiogenesis by reducing the expression of EPLIN." (PMID 34616746, 2021).
MIR93 also shares sentences with these, for which no sentence is quoted: benign tumors (1 paper); breast carcinoma (1); insomnia (1); metastatic tumors (1); mucinous adenocarcinoma (1); ovarian tumors (1); pancreatic adenocarcinoma (1); prostate carcinoma (1).